CORO1C (coronin 1C)
Diseases named in the same sentence as CORO1C in open-access papers (continued):
Sharing a sentence is not in itself a finding about the gene and the disease.
spinal muscular atrophy (1 paper, 2020). A motor neuron disease that affect the muscles, and characterized by muscle weakness and atrophy resulting from progressive degeneration and irreversible loss of the anterior horn cells in the spinal cord (i.e., lower motor neurons) and the brain stem nuclei. "For example, in Spinal Muscular Atrophy, the genes Plastin-3 (PLS3) and Coronin 1C (CORO1C) were identified as protective modifiers, unraveling impaired endocytosis as a rescue mechanism for the phenotype." (PMID 32671069, 2020).
Stroke (1 paper, 2022). Sudden impairment of blood flow to a part of the brain due to occlusion or rupture of an artery to the brain. "Furthermore, coronins, specifically overexpression of coronin-1C, has been implicated in several cancers, therefore, it may be an interesting starting point for the study of stroke-related tumors." (PMID 35518205, 2022).
tumor (28 papers, 2010 to 2026). "CORO1C has been implicated in cell migration and invasion in several studies; however, its role as a driver in the tumor types examined here remains unestablished and requires further validation." (PMID 41343608, 2025). "The presence of CORO1C amongst these neoplasms might aid a possible poor prognostic biomarker associated with the metastatic capacity of the tumour and its spread." (PMID 36649032, 2023). "Loss of Coronin 1C in this model increases both primary tumor growth rates and distant metastases." (PMID 32686704, 2020). "Coronin-1C protein is implicated to participate in various cellular events, such as cell migration, gene regulation, apoptosis, signal transduction, cell cycle progression, tumor cell metastasis, and the regulation of leukocyte-specific signaling events in innate immunity." (PMID 34959561, 2021). "Significant differences in CORO1C levels were observed between all grades, with grade 4 tumours exhibiting much higher CORO1C levels than lower-grade tumours." (PMID 40596133, 2025). "Downregulation of CORO1C/TPM3 signaling also contributed to the inhibition of EC tumor metastasis in vivo." (PMID 38540273, 2024). "The inhibition of MALAT1 upregulated the expression of miR-1-3p via a ceRNA mechanism, which subsequently suppressed tumor cell metastasis and tumor angiogenesis by inactivating the downstream effectors Coronin-1C (CORO1C) and tropomyosin 3 (TPM3)." (PMID 38540273, 2024). "The expression of CORO1C in astroglia cells and tumour cells is related to migrative and proliferative phenotypes." (PMID 36649032, 2023). "In NSCLC, miR-206 can inhibit the expression of coronin 1C (CORO1C) to negatively regulate the tumor metastasis." (PMID 35592419, 2022). "Together, these data show that deletion of Coronin 1C from the tumor cells in this model leads to significantly accelerated primary tumor growth and a trend toward enhanced metastasis." (PMID 32686704, 2020). "Based on these expression data showing Coronin 1C overexpression/upregulation in many aggressive cancers, we expected that deletion of Coronin 1C would yield a less aggressive tumor with fewer metastases." (PMID 32686704, 2020). "Taken together, these findings suggest the importance of elevated coronin-1C in tumour progression and metastasis." (PMID 28302118, 2017). "We had explored the relationship between coronin-1C expression and tumor spontaneous pulmonary metastasis in the nude mice model of HCC by IHC." (PMID 20181269, 2010). "In summary, YBX1 promotes tumor progression through its transcription factor activity, exerting its effects via various downstream targets such as MUC1, CDC25a, NANOG, Kindlin-2, G3BP1, AURKA, SPP1, the EGFR-RAS-MAPK axis, CORO1C, among others, depending on the specific tumor type." (PMID 40799245, 2025). "A significant increase in CORO1C expression was also observed with advancing tumour grade." (PMID 40596133, 2025). "Our IHC findings revealed that CORO1C expression increases with tumour grade, suggesting that highly metabolically active malignancies, such as MB and GB, might require increased expression of this protein for proliferation and metastasis." (PMID 40596133, 2025). "Downregulation of these tumor-suppressive miRNAs may be a key factor in the molecular mechanism leading to overexpression of CORO1C in PDAC cells." (PMID 37239355, 2023). "This further supported the evidence that CORO1C could be exponentially expressed in tumours with malignant and invasive properties and hence could serve as a biomarker associated with an unfavorable prognosis." (PMID 36649032, 2023). "Thus, it is a very interesting finding that CORO1C expression is regulated by multiple tumor-suppressive miRNAs." (PMID 37239355, 2023). "Potential miRNA tumour suppressors might aid helpfully in targeting CORO1C, rescuing its oncogenic phenotype." (PMID 36649032, 2023). "Several studies suggested a critical role of CORO1C in tumor metastasis." (PMID 34179087, 2021).
tumor (continued). "In addition, the TIMER online tool was exerted to evaluate the potential relationships between the expression of CORO1C and both tumor purity score as well as six types of tumor-infiltrating immune cells." (PMID 32695668, 2020). "In addition, high expression of CORO1C was found to be significantly correlated with tumor-infiltrating neutrophils (TINs), a negative regulatory component that facilitates tumor distant progression and induces poor clinical outcome." (PMID 32695668, 2020). "Among them, CORO1C has been demonstrated to play a vital role in tumor metastasis." (PMID 32206066, 2020). "Thus, all these results indicate that miR-206 negatively regulates tumor metastasis by directly targeting CORO1C." (PMID 32206066, 2020). "Its target, CORO1C, has been shown to regulate the formation and maintenance of lamellipodia, which are sheet-like cell protrusions involved in cell migration which could directly impact tumour cell migration." (PMID 40596133, 2025). "Thus, the expression of CORO1C is possibly dependent on tumour type and grade." (PMID 36649032, 2023). "Furthermore, CORO1C knockdown could decrease the cell proliferation, colony formation, migration and invasion in vitro and tumor growth in vivo." (PMID 34179087, 2021). "The tumor promoting role of CORO1C might be mediated by cyclin D1 and vimentin." (PMID 30974047, 2019). "miR-1 acts as a tumor suppressor, promoting the inhibition of tumor growth and acting with multiple target genes, such as CDK4, TMSB4X, WASF2, TWF1, CNN3, and CORO1C which are genes involved in cell cycle and metastasis." (PMID 38813102, 2024). "First, higher levels of CORO1C and RAD23B expression were positively correlated with tumor invasive depth, distant metastasis (M staging), and/or LNM (N staging)." (PMID 35589723, 2022). "The expression of CORO1C and TMPRSS4 in normal bladder tissues and the relationship between two genes and tumor stage were explored via GEPIA online tool." (PMID 32695668, 2020). "In contrast, positive immunostaining for CORO1C, RAD23B, and ARPC5 was observed in 55.7% (535/961), 84.0% (420/500), and 85.8% (429/500) of the CRC tumor tissues, respectively, showing significant upregulation compared with the adjacent noncancerous tissues (all P < 0.0001)." (PMID 35589723, 2022). "Surprisingly, we found that primary tumor growth was accelerated without Coronin 1C and that both macroscopic and microscopic metastatic events were more frequent." (PMID 32686704, 2020). "In conclusion, our study first identified CORO1C and TMPRSS4 as vital regulators in the process of tumor progression through influencing EMT and could be developed to effective prognostic and therapeutic targets in future BC treatment." (PMID 32695668, 2020). "Coronin-1C, a promising candidate, was found to be overexpressed in HCCLM9 cells as compared with MHCC97L cells, and validated by western blot and IHC from both nude mice tumor tissues and clinical specimens." (PMID 20181269, 2010). "The absence of CORO1C across the T-cell cluster might be explained by the fact that GBM neoplasms suppress T-cells, allowing neoplastic cells an immune-checkpoint escape and further proliferation." (PMID 36649032, 2023). "Currently, there are no relevant studies on the CORO1C, RAD23B, and ARPC5 proteins in CRC, except for our very recent work, which showed that RAD23B was overexpressed in CRC tumor tissues and associated with pathological grade, TNM staging, liver metastasis, and poor overall survival." (PMID 35589723, 2022). "Combined with the findings that the CORO1C, RAD23B, and ARPC5 concentrations in urine show good performance in distinguishing early-stage CRC (stage 0 and stage I) from HCs, these findings strongly suggest alterations in urinary proteins may occur at the tumor initiation stage." (PMID 35589723, 2022).
cancer (24 papers, 2010 to 2025). A tumor composed of atypical neoplastic, often pleomorphic cells that invade other tissues. "Coronin 1C is highly expressed in invasive human cancers and correlates positively with increased metastatic risk." (PMID 33050649, 2020). "CORO1C, a member in the Coronin gene family, is associated to many cancers and brain development." (PMID 29745845, 2018). "The significant overexpression of CORO1C in the 61–80 age group also suggested its high expression in adult brain malignancies, such as GB." (PMID 40596133, 2025). "Previous functional analyses of CORO1C have shown that it functions as a cancer-promoting gene in several cancer cells." (PMID 37239355, 2023). "Aggressive cancer cell phenotypes, especially cancer cell migration and invasion, were inhibited by CORO1C knockdown." (PMID 37239355, 2023). "Even though this study provided a possible mechanism for a future therapeutic approach in targeting CORO1C in NSCLC, little is known about any induced metastatic properties of CORO1C in this type of cancer." (PMID 36649032, 2023). "Overexpression of CORO1C in cancer cells has been reported in a wide range of cancers, and its overexpression contributes to cancer cell migration and invasion." (PMID 34884487, 2021). "The TMSB4X, CNN3, TWF1, CORO1C and WASF2 genes encode cytoskeletal proteins related to actin filament dynamic regulation, and they are involved in cancer metastasis." (PMID 28159933, 2017). "Key genes (ACTIN1, LIMK1, CORO1C, INF2, SH3D21, CFL1, FSCN1, MYO1B) implicated in actin cytoskeleton organization were identified, suggesting their role in oral potentially malignant disorders and cancer progression." (PMID 40818124, 2025). "The elevated expression of CORO1C in high grade metastatic brain malignancies, including GBM, suggests that this protein could have a clinical utility as a biomarker linked to an unfavorable outcome." (PMID 36649032, 2023). "The multifaceted functions of CORO1C enable it to activate various molecular pathways, which may accelerate the malignant transformation of cancer cells." (PMID 37239355, 2023). "CKS2 and CORO1C participate in the growth, invasion, and prognosis of several types of cancers." (PMID 33968720, 2021). "Thus, our study provides strong evidence for the role of CORO1C in NSCLC metastasis and sheds new light on the clinical significance of CORO1C in cancer therapy." (PMID 32206066, 2020). "Our recent studies of lung SCC revealed that miR-1/miR-133a clustered miRNAs, miR-206 and the miR-29-family inhibited cancer cell migration and invasion through targeting of several oncogenic genes, such as coronin-1C (CORO1C), c-MET and lysyl oxidase like 2 (LOXL2)." (PMID 27765924, 2016). "As a result of the in silico analysis, two genes (CORO1C and CORO2A) were selected as candidate cancer-promoting genes that affect the prognosis of PDAC patients." (PMID 37239355, 2023). "Both PAR2 and PAR1 activation resulted in up-regulated expression of several genes (CD44, FOSL1, TNFRSF12A, RAB3A, COPEB, CORO1C, THBS1, SDC4) known to be important in cancer." (PMID 21072196, 2010). "Among them, we selected the actin-binding protein gene ANLN because our past studies showed that several actin-binding protein genes (CORO1C, FSCN1,LASP1 and MSN) were overexpressed in cancer tissues and were deeply involved in promoting human cancer cell migration and invasion." (PMID 28881803, 2017). "Previous studies reported an involvement of the paralog CRN2 (synonyms are: Coro1C, coronin 3, hCRNN4) in multiple types of cancer." (PMID 26373535, 2015). "For other coronin families that have not been analyzed in this study (especially, CORO1C, CORO2B, and CORO7 whose expressions are dysregulated in cancer tissues), it is essential to elucidate the molecular pathogenesis of OSCC." (PMID 34884487, 2021).
infection (5 papers, 2012 to 2024). The state of being infected such as from the introduction of a foreign agent such as serum, vaccine, antigenic substance or organism. "Interestingly, the integration of the functional genomics approach and GWAS data with the evolutionary genetics approach allowed us to identify reQTL for three genes, GFM1, CORO1C and CEP192, that likely have a major role against infection with M. leprae and/or T1R." (PMID 28793313, 2017).
CORO1C also shares sentences with these, for which no sentence is quoted: primary effusion lymphoma (3 papers); dyslipidemia (1); head and neck cancer (1); influenza (1); leprosy (1); lung adenocarcinoma (1); lung diseases (1); Lymphatic Metastasis (1); macrosomia (1); schizophrenia (1); type 2 diabetes (1).